ANGPTL8 (angiopoietin like 8)
Diseases named in the same sentence as ANGPTL8 in open-access papers (continued):
Sharing a sentence is not in itself a finding about the gene and the disease.
psoriasis (3 papers, 2020 to 2023). An autoimmune condition characterized by red, well-delineated plaques with silvery scales that are usually on the extensor surfaces and scalp. "Taking into account the significant role of the described protein in many CMDs, it seems advisable to conduct research and broaden the knowledge about the diagnostic and clinical role of ANGPTL8 in psoriasis." (PMID 36983346, 2023). "The applicability of serum levels of calprotectin and ANGPTL8 for monitoring of the activity of psoriasis (diagnostic markers) is also evaluated." (PMID 32537470, 2020). "The paper also evaluates the applicability of serum levels of calprotectin and ANGPTL8 for monitoring of the activity of psoriasis (diagnostic markers)." (PMID 32537470, 2020). "Furthermore, we aimed to measure the clinical significance of ANGPTL8 in psoriasis and its potential importance in estimating the risk of CMDs in patients with psoriasis." (PMID 36983346, 2023). "A putative link between ANGPTL8 and psoriasis also appears to be the myokine irisin which has been found to increase ANGPTL8 expression during adipocyte differentiation." (PMID 36983346, 2023). "We aimed to evaluate the serum concentration of ANGPTL8 in individuals with psoriasis and examine how systemic therapy affects the concentration of ANGPTL8." (PMID 36983346, 2023). "The average concentration of ANGPTL8 differed significantly between the psoriasis group (before and after therapy) and the control group (p < 0.05)." (PMID 36983346, 2023). "Nevertheless, future studies on a larger number of enrolled patients are required to find out the role of ANGPTL8 in such a complex disease as psoriasis." (PMID 36983346, 2023). "We suspect ANGPTL8 to act as a potentially protective agent in psoriasis in terms of cardiometabolic complications development." (PMID 36983346, 2023). "The highest concentration of ANGPTL8 was found among patients with mild psoriasis and a lower concentration in the other two groups with more severe skin lesions." (PMID 36983346, 2023). "A presumed common link between ANGPTL8 and psoriasis seemed to be mediated by myokine called irisin." (PMID 32456228, 2020). "Accumulated data have highlighted that increased levels of ANGPTL8 were observed in obesity, which is closely linked with CMS and also psoriasis." (PMID 32456228, 2020). "The study describes the influence of psoriasis and MetS on the serum indicators of systemic inflammation (calprotectin and ANGPTL8) and on the serum indicators of oxidative damage to nucleic acids." (PMID 32537470, 2020). "The presented study describes the influence of psoriasis and MetS on the serum levels of markers of systemic inflammation (calprotectin and ANGPTL8) and markers of oxidative damage to nucleic acids." (PMID 32537470, 2020). "Today, the exact role of ANGPTL8 in inflammatory processes and subsequently in the course of psoriasis is still poorly understood." (PMID 32456228, 2020). "In subjects with mild psoriasis, the impact of ANGPTL8 seems most significant." (PMID 36983346, 2023). "Therefore, we intended to explore the potential interplay between ANGPTL8 and the complexity of psoriasis." (PMID 36983346, 2023). "The specific involvement of ANGPTL8 in inflammatory processes and, as a result, in the progression of psoriasis is still unknown." (PMID 36983346, 2023). "Another possible link between ANGPTL8 and psoriasis might be its involvement in innate and adaptive immune responses, although the data are conflicting." (PMID 36983346, 2023). "The same group showed that ANGPTL8 levels are elevated in patients with diagnosed CMS and this dependency was significantly associated with hs-CRP levels, highlighting its potential role in metabolic and inflammatory pathways that are crucial in the course of psoriasis." (PMID 32456228, 2020). "It seems that the serum level of calprotectin (but not serum level of ANGPTL8) could be used as a biomarker for monitoring the activity of psoriasis (diagnostic marker)." (PMID 32537470, 2020).
psoriasis (continued). "Despite this, there exists a strong basis for future research aimed at enhancing our comprehension of the interplay between ANGPTL8 and CMS inflammation in individuals with psoriasis." (PMID 36983346, 2023). "The presence of MetS did not significantly affect the serum levels of calprotectin, ANGPTL8, and oxidative damage to nucleic acids in either psoriasis patients or controls." (PMID 32537470, 2020). "The psoriasis significantly increased the serum level of calprotectin and the serum level of oxidative damage to nucleic acids, however not the serum level of ANGPTL8." (PMID 32537470, 2020). "Nevertheless, there is a strong background for further studies that may increase our knowledge of the interplay of ANGPTL8 and CMS inflammation in patients diagnosed with psoriasis." (PMID 32456228, 2020). "It seems that the serum level of calprotectin (but not the serum level of ANGPTL8) could be used as a biomarker for monitoring the activity of psoriasis." (PMID 32537470, 2020). "The results of the study show that psoriasis significantly increased the serum level of calprotectin (indicator of systemic inflammation) and the serum level of oxidative damage to nucleic acids, however not the serum level of ANGPTL8 (indicator of systemic inflammation)." (PMID 32537470, 2020).
cardiac hypertrophy (2 papers, 2022 to 2023). "To further elucidate the underlying mechanism of ANGPTL8 against pathological cardiac hypertrophy, we performed Kyoto Encyclopedia of Genes and Genomes pathway enrichment analysis based on an RNA-seq data set from ANGPTL8-KO and WT hearts treated with Ang II." (PMID 35851270, 2022). "In the Ang II- and transverse aortic constriction (TAC)-induced mouse cardiac hypertrophy model, ANGPTL8 deficiency remarkably accelerated cardiac hypertrophy and fibrosis with deteriorating cardiac dysfunction." (PMID 35851270, 2022). "In parallel, in the experimental mouse model of TAC- and Ang II-induced cardiac hypertrophy, serum ANGPTL8 levels were also dramatically increased." (PMID 35851270, 2022). "Taken together, these results indicated that secreted ANGPTL8 ameliorated cardiac hypertrophy by binding to the membrane receptor PIRB (LILRB3) to suppress Akt/GSK3β activity." (PMID 35851270, 2022). "We found that serum ANGPTL8 levels were significantly increased in hypertensive patients with cardiac hypertrophy and in mice with cardiac hypertrophy induced by Ang II or TAC." (PMID 35851270, 2022). "In this study, we found that ANGPTL8 ablation aggravated cardiac hypertrophy and fibrosis in TAC and Ang II infusion-induced cardiac hypertrophy models." (PMID 35851270, 2022). "We aimed to investigate the role of angiopoietin-like protein 8 (ANGPTL8) in pathological cardiac hypertrophy." (PMID 35851270, 2022). "Collectively, our results delineated that ANGPTL8 ameliorated the development of pathological cardiac hypertrophy via the LILRB3-Akt/GSK3β signaling cascade." (PMID 35851270, 2022). "Consistently, ANGPTL8 overexpression alleviated cardiac hypertrophy induced by Ang II, leading to a damper response to Ang II-induced hypertrophy based on the analysis of cell surface area and the expression level of β-MHC." (PMID 35851270, 2022). "As a secreting hormone, ANGPTL8 is unable to penetrate cell membranes to regulate cardiac hypertrophy, so we explored the potential ANGPTL8 receptors on the cell membranes of cardiomyocytes." (PMID 35851270, 2022). "ANGPTL8 exerts a cardioprotective effect on pathological cardiac hypertrophy by negatively regulating the Akt/GSK3β signaling pathway." (PMID 35851270, 2022). "Herein, we found that PIRA1, PIRA2 and PIRB expression was significantly upregulated in the cardiac hypertrophy model in WT mice compared with ANGPTL8 KO mice." (PMID 35851270, 2022). "Altogether, these findings indicated that ANGPTL8 KO dramatically aggravated cardiac hypertrophy and fibrosis induced by Ang II." (PMID 35851270, 2022). "Collectively, these results demonstrated that ANGPTL8, acting as a novel regulator, played a protective role in cardiac hypertrophy." (PMID 35851270, 2022). "Collectively, ANGPTL8 KO also promoted TAC-induced cardiac hypertrophy." (PMID 35851270, 2022). "Targeting ANGPTL8 may be a promising strategy for reversing pathological cardiac hypertrophy and provide synergistic effects in combination with AT1 blockers." (PMID 35851270, 2022). "All the results supported that ANGPTL8 regulated cardiac hypertrophy via the Akt/GSK-3β pathway." (PMID 35851270, 2022). "To verify whether the antihypertrophic effect of ANGPTL8 was limited to Ang II-induced cardiac hypertrophy, we adopted overload pressure-induced cardiac hypertrophy by TAC." (PMID 35851270, 2022). "Moreover, given that Akt signaling is a well-accepted key hub in pathological cardiac hypertrophy, we first assessed the potential involvement of Akt and downstream signaling in the antihypertrophic effect of ANGPTL8." (PMID 35851270, 2022). "Thus, cardiac hypertrophy may upregulate the expression of ANGPTL8 through certain mechanisms, and circulating ANGPTL8 can directly act on cardiomyocytes to exert anti-ventricular remodelling effects." (PMID 38107478, 2023).
cardiac hypertrophy (continued). "In mice with angiotensin II (Ang II)-induced cardiac hypertrophy or transverse aorta constriction (TAC)-induced cardiac hypertrophy, serum ANGPTL8 levels were also significantly increased." (PMID 38107478, 2023). "In summary, ANGPTL8, which binds to LILRB3, negatively regulates the development of pathological cardiac hypertrophy by inhibiting Akt/GSK3β activity." (PMID 35851270, 2022). "In an animal study, ANGPTL8 knockout accelerated Ang II- and TAC-induced cardiac hypertrophy, fibrosis and dysfunction." (PMID 35851270, 2022). "Therefore, we speculate that ANGPTL8 can directly interact with PIRs, especially PIRB, to provide a cardioprotective effect against cardiac hypertrophy." (PMID 35851270, 2022). "This evidence supports the hypothesis that ANGPTL8 may be a negative regulator in pathological cardiac hypertrophy; however, this hypothesis has still not been illustrated." (PMID 35851270, 2022). "However, lipid and glucose metabolic disorders did not occur in either Ang II- or TAC-induced cardiac hypertrophy models of WT and ANGPTL8 KO mice in our experiment; therefore, ANGPTL8 may act directly on the heart muscle to inhibit cardiac hypertrophy." (PMID 35851270, 2022).
Cirrhosis (2 papers, 2025). A chronic disorder of the liver in which liver tissue becomes scarred and is partially replaced by regenerative nodules and fibrotic tissue resulting in loss of liver function. "Indeed, chronic hepatic inflammation is the hallmark of steatohepatitis, and data indicate that ANGPTL8 is implicated in the regulation of pro-inflammatory pathways, including NF-κB signaling, which promote fibrosis and cirrhosis." (PMID 40276549, 2025). "One example of such differences between healthy and patients with cirrhosis is ANGPTL8, a protein known to increase in the circulation during a meal and that contribute to postprandial lipid metabolism." (PMID 40489530, 2025).
colon adenocarcinoma (2 papers, 2021 to 2023). "Conversely, ANGPTL8 levels are significantly increased in HCC, KIRC/ccRCC, colon adenocarcinoma (COAD), rectum adenocarcinoma (READ), and stomach adenocarcinoma (STAD)." (PMID 38107478, 2023).
Hyperinsulinemia (2 papers, 2020 to 2021). An increased concentration of insulin in the blood. "Factors that decrease the level of ANGPTL8 includes hyperinsulinemia, TNFα, miRNA 143-3p from hepatocytes, and miRNA 221-3p which expression is promoted by activated macrophages in adipose cells, glucocorticoids during fasting, etc.." (PMID 32537470, 2020).
macrosomia (2 papers, 2022 to 2023). "Moreover, future studies are needed to investigate whether the decreased production or secretion of ANGPTL8 from placenta could directly participate the development of GDM and macrosomia." (PMID 35529083, 2022).
nonalcoholic fatty liver (2 papers, 2020 to 2022). "Moreover, GLP-1R agonists stimulate ANGPTL8 production in human hepatocytes dose-dependently, and ANGPTL8 has been described as a novel vitamin D receptor target gene involved in nonalcoholic fatty liver pathogenesis." (PMID 32746907, 2020).
renal failure (2 papers, 2023 to 2024). "On the other hand, levels of ANGPTL8 were significantly reduced at a state of renal failure in patients with chronic haemodialysis; nonetheless, the regulatory mechanism causing the elimination of ANGPTL8 in end-stage renal disease is still obscure." (PMID 37762544, 2023).
Sepsis (2 papers, 2022 to 2024). Sepsis is defined as life-threatening organ dysfunction caused by a dysregulated host response to infection. "Collectively, our results indicated that inflammation caused by infection leads to a disorder of liver lipid metabolism and that ANGPTL8 deficiency improves the survival rate of mice with sepsis by suppressing the inflammatory response and improving PGC1α/PPARα-mediated lipid metabolism." (PMID 39019343, 2024). "This further supports the hypothesis of compensatory upregulation of circulatory betatrophin/ANGPTL8 under conditions of human sepsis for the purpose of neutralization of pathogen-associated lipids." (PMID 36551906, 2022). "To elucidate the mechanism by which ANGPTL8 regulates liver lipid metabolism during sepsis, we performed RNA-seq analysis of livers from WT and ANGPTL8 KO mice 48 h after LPS stimulation." (PMID 39019343, 2024). "Since sepsis is a syndrome of multiple-organ dysfunction, further exploration of the role of ANGPTL8 in lung injury, kidney injury, and other organ injury has guiding significance for the development of ANGPTL8-targeted therapy." (PMID 39019343, 2024). "Consistent with our hypothesis, genetic Angptl8 depletion reduced the mortality rate of mice with LPS-induced sepsis, which might be attributed to improved liver function." (PMID 39019343, 2024). "Therefore, targeting ANGPTL8 to improve liver lipid metabolism represents an attractive strategy for the management of sepsis patients." (PMID 39019343, 2024). "Therefore, inhibition of ANGPTL8 expression can improve metabolic disorders and the prognosis of sepsis patients." (PMID 39019343, 2024). "Since blood samples were taken after surgery in the sepsis group, propofol could theoretically have influenced circulating triacylgylceride levels and accordingly betatrophin/ANGPTL8 in an indirect manner." (PMID 36551906, 2022). "Inhibitors of ANGPTL8 may reduce organ damage and improve the prognosis of sepsis patients." (PMID 39019343, 2024). "In vivo studies revealed that although TNF-α receptor inhibitors improve liver lipid deposition and peroxidation, they do not improve the survival rate of mice with sepsis as much as knocking out Angptl8 does." (PMID 39019343, 2024).
acromegaly (1 paper, 2023). Acromegaly is an acquired disorder related to excessive production of growth hormone (GH) and characterized by progressive somatic disfigurement (mainly involving the face and extremities) and systemic manifestations. "In this study, we evaluated the risk of NAFLD and hepatic fibrosis in patients with acromegaly and their association with the noninvasive scores and ANGPTL-8 levels for the first time in the literature." (PMID 37590020, 2023). "Serum ANGPTL-8 levels, IGF-1, and GH were significantly lower in those with NAFLD in the acromegaly group." (PMID 37590020, 2023). "Moreover, the utility of the NS and the link between NAFLD and ANGPTL-8 in acromegaly is unknown." (PMID 37590020, 2023). "Although noninvasive scores and serum ANGPTL-8 levels have been investigated in patients without acromegaly but with NAFLD, their utility in acromegaly remains uncertain." (PMID 37590020, 2023). "Interestingly, non-NAFLD acromegalic patients showed higher serum ANGPTL-8 levels than patients with acromegaly with NAFLD in our study." (PMID 37590020, 2023). "Patients with acromegaly with NAFLD had lower GH, IGF-1, and ANGPTL-8 levels than in those without NAFLD (P = .025, P = .011, and P = .036, respectively)." (PMID 37590020, 2023). "The median ANGPTL-8, GH, and IGF-1 levels of the patients with NAFLD were lower than those without NAFLD in the whole acromegaly group." (PMID 37590020, 2023).
alcohol (1 paper, 2022). "Chronic alcohol decreased the expression of Angptl8 by 75%, and Cili rescued such a downregulation." (PMID 35565941, 2022).
Anorexia (1 paper, 2021). Lack of desire to eat (loss of appetite). "On the other hand, ANGPTL8 is also involved in the regulation of appetite, that is, the increase of ANGPTL8 is related to the occurrence of anorexia, and neuropeptide Y-positive neurons in the dorsal medial hypothalamic nucleus may be involved in it." (PMID 34582711, 2021).
endothelial dysfunction (1 paper, 2025). In vascular diseases, endothelial dysfunction is a systemic pathological state of the endothelium (the inner lining of blood vessels) and can be broadly defined as an imbalance between vasodilating and vasoconstricting substances produced by (or acting on) the endothelium. "There is interest in ANGPTL8 levels and their suitability to gauge endothelial dysfunction and grade of stenosis in coronary arteries." (PMID 40725697, 2025).